DIPK2B (divergent protein kinase domain 2B)
Synonyms: CXorf36; DIA1R; FLJ14103; 4930578C19Rik; EPQL1862; PRO3743; bA435K1.1
Tractability: Antibody: UniProt places it where antibodies can reach, with high confidence; UniProt predicts a signal peptide or a membrane-spanning region; its Gene Ontology location is reachable by antibodies, with medium confidence. PROTAC: ubiquitination databases record sites on it.
Gene: Protein-coding gene on chromosome X (45,148,373 to 45,200,963, reverse strand). Ensembl gene ENSG00000147113.
Subcellular location: Secreted
Gene Ontology:
Cellular component: extracellular region
Homologues: Orthologues: chimpanzee DIPK2B (99% identical), macaque DIPK2B (97% identical), rabbit DIPK2B (86% identical), pig DIPK2B (85% identical), mouse Dipk2b (81% identical), rat Dipk2b (80% identical), guinea pig DIPK2B (70% identical), zebrafish dipk2b (44% identical), Drosophila melanogaster CG11170 (15% identical). Paralogues in human: DIPK2A (30% identical).
Diseases named in the same sentence as DIPK2B in open-access papers:
DIPK2B is named in the same sentence as 13 diseases in open-access papers, as found by Europe PMC text mining. Sharing a sentence is not in itself a finding about the gene and the disease. The quoted sentences say what the papers report.
autism (5 papers, 2011 to 2025). Persistent deficits in social interaction and communication and interaction as well as a markedly restricted repertoire of activity and interest as well as repetitive patterns of behavior. "Several of these functionally uncharacterized proteins are associated with human diseases including ciliary dyskinesia (CLXN), Lui-Jee-Baron syndrome (SPIN4), lymphoblastic leukemia (LNP1, SLX4IP), lethal skeletal dysplasia (TMEM263), and association to autism and fragile X syndrome (DIPK2B)." (PMID 40425816, 2025). "Dipk2b has been reported to alter neuronal cellular secretory pathways that are involved in autism while RAB37 is known to participate in membrane trafficking and in the regulation of TIMP1 exocytosis." (PMID 38351172, 2024).
dyslipidemia (1 paper, 2023). "Other variants associated with CI2 were observed on KCND3, DIPK2B, and LIPC/ALDH1A2, which have already been identified in lipoprotein and dyslipidemia studies." (PMID 37372394, 2023).
DIPK2B also shares sentences with these, for which no sentence is quoted: fragile X syndrome (2 papers); neurological diseases (2); autism spectrum disorder (1); cancer (1); ciliary dyskinesia (1); Kabuki syndrome (1); Lethal skeletal dysplasia (1); Lui-Jee-Baron syndrome (1); lymphoblastic leukemia (1); mental retardation (1); schizophrenia (1).